RN7SL754P (RNA, 7SL, cytoplasmic 754, pseudogene)
Gene: Miscellaneous RNA gene on chromosome 10 (430,239 to 430,504, reverse strand). Ensembl gene ENSG00000239822.
Homologues: Orthologues: chimpanzee Metazoa_SRP (98% identical), macaque Metazoa_SRP (83% identical). Paralogues in human: RN7SL1 (77% identical), RN7SL3 (77% identical), RN7SL197P (77% identical), RN7SL2 (77% identical), Metazoa_SRP (76% identical), RN7SL220P (76% identical), RN7SL627P (76% identical), RN7SL126P (76% identical), RN7SL448P (76% identical), RN7SL620P (75% identical), RN7SL91P (75% identical), RN7SL18P (74% identical), and 699 more.